RNU6-21P (RNA, U6 small nuclear 21, pseudogene)
Synonyms: RNU6-21
Gene: Small nuclear RNA gene on chromosome 16 (62,187,540 to 62,187,646, reverse strand). Ensembl gene ENSG00000207441.
Homologues: Orthologues: chimpanzee U6 (98% identical), dog U6 (94% identical), mouse Gm25457 (93% identical), mouse Gm26335 (92% identical), guinea pig U6 (87% identical), dog U6 (86% identical), dog U6 (83% identical). Paralogues in human: RNU6-1 (95% identical), RNU6-15P (95% identical), RNU6-2 (95% identical), RNU6-3P (95% identical), RNU6-4P (95% identical), RNU6-5P (95% identical), RNU6-6P (95% identical), RNU6-9 (95% identical), RNU6-12P (94% identical), RNU6-13P (94% identical), RNU6-17P (94% identical), RNU6-18P (94% identical), and 1285 more.